GLP1R (glucagon like peptide 1 receptor)
Diseases named in the same sentence as GLP1R in open-access papers (continued):
Sharing a sentence is not in itself a finding about the gene and the disease.
Cognitive impairment (41 papers, 2014 to 2026). Abnormal cognition is characterized by deficits in thinking, reasoning, or remembering. "Similarly, several evidences demonstrated that treatment with glucagon-like peptide-1 receptor agonists (GLP-1 RAs) reduces the risk of cognitive impairment and dementia in T2DM patients by improving learning, memory, attention and executive functions." (PMID 41480353, 2025). "However, our research is still worthy of attention as our experiments have established that both GLP-1R and autophagy are effective therapeutic targets for cognitive impairment caused by dietary salt." (PMID 38575652, 2024). "Cerebral GLP‐1R activation can effectively ameliorate neuropathological changes and cognitive impairment following TBI; the underlying mechanism could involve the repair of the glymphatic system damaged by TBI." (PMID 37353947, 2023). "Cerebral GLP‐1R activation can effectively ameliorate neuropathological changes and cognitive impairment following traumatic brain injury, and the underlying mechanism could involve the repair of the glymphatic system damaged by traumatic brain injury." (PMID 37353947, 2023). "This meta-analysis examines the association of cardioprotective glucose-lowering agents, including glucagon-like peptide-1 receptor agonists and sodium-glucose cotransporter-2 inhibitors, with reductions in dementia and cognitive impairment." (PMID 40193122, 2025). "In this context, glucagon-like peptide-1 receptor agonists (GLP-1RAs) are being proposed as potential drugs for managing cognitive disorders owing to their putative ability to affect neurobiological and metabolic pathways implicated in neurodegeneration." (PMID 40210453, 2025). "Overexpression of GLP-1R in the hippocampus improves neurite growth and learning, while GLP-1R knockout results in cognitive deficits." (PMID 39574978, 2024). "In summary, our study demonstrated that a long-term HS diet can lead to cognitive impairment and impair the level of GLP-1R, and then activate mTOR/p70S6K pathway to inhibit autophagy flux." (PMID 38575652, 2024). "Our results are significant as they show that dietary salt leads to tau hyperphosphorylation, damages GLP-1R and activates mTOR/p70S6K pathway, which eventually leads to cognitive impairment in C57BL/6 mice." (PMID 38575652, 2024). "Glymphatic function suppression by treatment using aquaporin 4 inhibitor TGN‐020 abolished the protective effect of the GLP‐1R agonist against cognitive impairment." (PMID 37353947, 2023). "In the PD models, GLP1R agonists reduced the expression of proinflammatory cytokines and the degeneration of dopaminergic neurons, prevented cognitive impairment, and prolonged lifespan." (PMID 32635358, 2020). "Treatment with EX-4 prevented the cognitive deficit in the model and this effect was mediated by GLP-1R activation as it was blocked by co-administration of the competitive GLP-1R antagonist, EX9-39." (PMID 30618629, 2018). "And also GLP-1 and GLP-1R have been considered a therapeutic target in neurodegenerative and cognitive disorders throughout the central and peripheral nervous systems." (PMID 24741367, 2014). "However, we used GLP-1R agonists in vitro in this study, so further in vivo experiments are needed to confirm that the silence of GLP-1R can inhibit autophagy and lead to cognitive impairment by activating mTOR/p70S6K pathway." (PMID 38575652, 2024). "Furthermore, the ability of GLP-1R agonists to ameliorate neuropathy-related complications, such as cognitive deficits, underscores their broader neuroprotective benefits." (PMID 38997662, 2024). "Furthermore, several clinical studies demonstrated that glucagon-like peptide-1 receptor agonists (GLP-1RAs) can reduce the risk of dementia in T2DM patients by improving memory and learning and overcoming cognitive impairment." (PMID 38287296, 2024).
Cognitive impairment (continued). "Based on previous studies, we hypothesize that a long-term HSD regulates autophagic flux by impairing the level of GLP-1R, thereby damaging neurons and synapses, and subsequently leading to cognitive impairment." (PMID 38575652, 2024). "Moreover, activation of GLP‐1R enhances learning processes in cognitive impaired rodents tentatively by increasing neurogenesis and neuroplasticity." (PMID 32770792, 2021). "Additionally, decreased GLP-1R levels in obese or diabetic mice with cognitive impairment in multiple tissue, including brain were observed." (PMID 33298623, 2020). "Moreover, plasma GLP-1 levels decrease in APP23/PS45 mice and negatively correlate with brain Aβ load in AD patients, while an GLP-1R agonist improves cognitive impairment and lowers Aβ/β-CTF by reducing BACE1 expression in the hippocampus/cortex of APP23/PS45 mice." (PMID 41446639, 2025). "Similarly, activating GLP-1R helps to restore glymphatic transport and reduce cognitive impairment." (PMID 38253938, 2024). "Additionally, GIPR and GLP-1R knockout mice showed impairment of synaptic plasticity and cognitive deficit; however, in another study, GIPR knockout mice showed extended lifespan, as well as increased exploratory and decreased anxiety-based behaviors, indicating a divergent effect of incretins." (PMID 35008973, 2022). "GLP-1R plays an important role in synaptic plasticity and memory formation, GLP-1R-knockout mice show cognitive impairment." (PMID 40171533, 2025). "This systematic review focuses on the cognitive effects of semaglutide, a glucagon-like peptide 1 receptor agonist (GLP-1 RA), in the context of neurological and cognitive impairment." (PMID 38732190, 2024). "Third, the cognitive impairment induced by ketamine was reversed by PROG and ALLO add-on treatments, and the PGRMC1/EGFR/GLP-1R/PI3K/Akt pathway was upregulated." (PMID 33767621, 2021).
Anxiety (37 papers, 2018 to 2026). Intense feelings of nervousness, tension, or panic often arise in response to interpersonal stresses. "We also observed statistically significant association between GIPR rs1800437 GG genotype and BSPS scores in the abstinent alcohol-dependent patients as well as the association between GLP1R rs6923761 GG genotype and Zung anxiety scores in healthy controls." (PMID 35754710, 2022). "Also, in alcohol-dependent rodents, administration of GLP-1R agonists mitigated signs of alcohol withdrawal and associated anxiety-like behavior." (PMID 41508124, 2026). "Interestingly, improvements in anxiety-like behavior after loss of GLP-1R were only noted in females, potentially suggesting females rely more on this system to maintain a baseline of normal anxiety-like behavior." (PMID 39715341, 2025). "In rodent models, GLP-1R agonists (liraglutide or exenatide) increase anxiety behaviors, and anxiogenic effects may be associated with an acute increase in corticosterone and ACTH." (PMID 38067196, 2023). "GLP-1 and GLP-1R enhance the behavioral response of mice to cocaine, and the loss of GLP-1R could regulate the anxiety-related behavior." (PMID 36590616, 2022). "Statistically significant association between GIPR rs1800437 GG genotype and Brief Social Phobia Scale scores were observed in the abstinent alcohol-dependent patients, while GLP1R rs6923761 GG genotype was associated with Zung anxiety scores in healthy controls." (PMID 35754710, 2022). "However, GLP1R rs6923761 AA genotype was associated with lower Zung anxiety scores among healthy controls (p = 0.021)." (PMID 35754710, 2022). "In animal models, GLP-1R activation dampens effort-based seeking for palatable food and addictive drugs alike, exerts bidirectional effects on affective behavior (e.g., anxiety-like behavior), and promotes synaptic plasticity, learning, and neuroprotection." (PMID 41876956, 2026). "First, while GLP1R activation induces anxiety-like behaviors and activates the HPA axis, it is still unclear to what extent endogenous GLP-1 release from PPG neurons drives these effects under physiological conditions." (PMID 41222078, 2025). "Preclinical and genetic studies link GLP1R activation to anti-inflammatory, and neurotrophic and neuroplastic effects, benefiting mood, anxiety, and reward-related disorders." (PMID 41302345, 2025). "The SMR analysis showed that each standard deviation increase in GLP1R gene expression (the target of the GLP-1 receptor, probe: ENSG00000112164) was associated with a reduced risk of anxiety (OR:0.79, 95% CI:0.64–0.98, P = 0.031)." (PMID 41331950, 2025). "Specifically, abstinence symptoms during withdrawal such as anxiety is prevented by liraglutide (the GLP-1R agonist) or sitagliptin (a DPP-IV inhibitor that enhances endogenous GLP-1)." (PMID 36699502, 2022). "These include but are not limited to anxiety and stress, which are processes that GLP‐1R agonists alter." (PMID 32770792, 2021). "In other brain regions, such as the BNST, the center of integration for limbic information regulates the affective and physiological components of anxiety, GLP-1R blockade attenuates stress-induced hypophagia in mice." (PMID 33126672, 2020). "Moreover, acute central administration of GLP‐1 RAs activates GLP‐1R in the raphe nucleus, directly inducing anxiety‐like behaviors." (PMID 40887719, 2025). "The HEIDI test indicated that the association between GLP1R and anxiety was not driven by linkage disequilibrium." (PMID 41331950, 2025). "Since the BNST also expresses GLP1R and their ablation reduces anxiety-like behaviors, this could provide another potential convergence mechanism by which semaglutide or other GLP1R could affect cannabis consumption." (PMID 38486046, 2024). "Moreover, as the outcome of GLP-1R activation on anxiety-like behavior are inconsistent and depend on contextual factors the possible influence on such behavior is complex." (PMID 36229445, 2022).
Anxiety (continued). "Otherwise, initiation of fear and sustained anxiety responses requires the recruitment of the BNST, knocking down the translation of GLP1-R mRNA in the anterolateral BNST in rats, decreases anxiety-like behavior in the open field test, including a loss of light-enhanced acoustic startle." (PMID 33126672, 2020). "WGCNA revealed 58 modules with a close relationship between the microglial GLP-1R pathway and features of nerve injuries, including pain, ligation, paw withdrawal latency (PWL), and anxiety." (PMID 34512747, 2021). "As well, Glp1r knockdown in neurons expressing single-minded 1, a transcription factor abundantly expressed in the PVN in mice, reduced anxiety-like behavior." (PMID 33126672, 2020). "The central administration of a GLP-1R antagonist blocks the plasma increase of ACTH and corticosterone induced by the EPM and decreases anxiety-like behaviors in the EPM, indicating that central nervous system (CNS) GLP-1 mediates anxiety responses." (PMID 33126672, 2020). "With respect to stress and anxiety, we identified Glp1r, which directly interacts with the HPA axis to trigger the secretion of glucocorticoids and Gpr3 which modulates anxiety- and depressive-related behaviors by regulating monoaminergic neurotransmitters and their metabolites." (PMID 37228107, 2023). "Overall, the data show that activation of the GLP-1R neurons in mice leads to repetitive behaviors that are not due to increased anxiety levels but remarkably suppressed feeding behavior." (PMID 36309763, 2022). "Notably, the vast majority of studies suggest that acute injections of GLP-1R or GLP-1R/GIPR dual agonists do not adversely affect anxiety, visual function, exploratory or locomotor behavior." (PMID 36117625, 2022). "Additionally, potential effects on nausea, stress and anxiety, which are known effects of GLP-1R agonists, were not assessed, which could have influenced the statistical outcomes." (PMID 40245495, 2025).
pancreatic cancer (35 papers, 2011 to 2026). "In that study, the combination of GLP-1R therapy and insulin predicted a greater risk for pancreatic cancer compared with GLP-1R monotherapy, consistent with a reported tumor-promoting role of insulin in preclinical pancreatic cancer models." (PMID 41178720, 2025). "This cohort study evaluates the association of glucagon-like peptide-1 receptor agonist (GLP-1RA) treatment with pancreatic cancer incidence over 9 years of follow-up." (PMID 38175642, 2024). "Chronic pancreatitis represents a prevalent risk factor for the development of pancreatic cancer, thus necessitating more scrutiny of the association between GLP-1R agonists and the induction of chronic pancreatitis." (PMID 37958889, 2023). "A recent retrospective cohort study similarly showed that GLP-1R agonist use was associated with a lower risk of pancreatic cancer compared with use of several other antihyperglycemic drugs, including insulin, metformin, DPP4 inhibitors, SGLT2 inhibitors, sulfonylurea, or thiazolidinediones (TZDs)." (PMID 41178720, 2025). "Concerns have been raised that glucagon-like peptide-1 receptor agonists (GLP-1RA) may increase the risk of pancreatic cancer." (PMID 38175642, 2024). "Nonexpression of GLP-1R is common in advanced pancreatic tumors with lymphatic metastasis and is associated with poor prognosis, suggesting that GLP-1R may inhibit tumorigenesis and metastasis of human pancreatic cancer cells both in vitro and in vivo." (PMID 39371922, 2024). "Although GLP-1R agonists offer numerous benefits in the management of type 2 diabetes, it is imperative to no longer disregard the potential risk they pose in terms of pancreatic cancer development." (PMID 37958889, 2023). "By analyzing the reported adverse events in the US Food and Drug Administration’s database, Elashoff reported that treatment with DPP4 inhibitor sitagliptin or GLP-1R agonist exenatide increased the risk of pancreatitis and pancreatic cancer as compared with other therapies." (PMID 36569936, 2022). "Liraglutide suppresses protein kinase B (Akt) phosphorylation in pancreatic cancer cells by activating GLP-1R, thus inhibiting tumor growth via suppression of the PI3K/Akt signaling pathway." (PMID 40140925, 2025). "GLP1R expression was significantly elevated in pancreatic tumors compared to normal pancreatic tissues, with the median expression reaching around 200 in tumors while remaining close to zero in normal tissues." (PMID 39777709, 2025). "Associations of ABCC8/KCNJ11, DPP4, GLP1R, GPD2, PPARG, PRKAB1, and SLC5A2 with anal carcinoma, cardia cancer, gastric cancer, HCC, ICC, pancreatic cancer, and rectum cancer were revealed in two-sample MR analyses." (PMID 38504335, 2024). "GLP-1R expression was found to be lower in gemcitabine-resistant pancreatic cancer cell line PANC-GR compared to human pancreatic cancer cell line PANC-1." (PMID 39931650, 2024). "Due to the promotive effect of GLP-1R agonism on β-cells proliferation and survival, concerns of tumorigenesis, especially pancreatic cancers, have been raised about incretin-based therapies." (PMID 36569936, 2022). "Pancreatic cancer cell lines and mouse xenograft models of human pancreatic cancer were used to evaluate the effects of the GLP-1R agonist liraglutide in vitro and vivo." (PMID 36569936, 2022). "GLP-1R protein expression was finally detected by a top cited and validated antibody, whose specificity was further proven in capan-1 cell lysate, a pancreatic cancer cell line expressing GLP-1R." (PMID 35397526, 2022). "The results demonstrated that GLP-1R activation with liraglutide dose-dependently suppressed Akt activation and tumourigenicity/metastasis in human pancreatic cancer cells both in vitro and in vivo." (PMID 36569936, 2022). "This study has shown that the combination of GLP1-R targeted Auger emitter radiation therapy with an anti-angiogenic compound has a synergistic effect on the pancreatic tumors of the Rip1Tag2 transgenic mice." (PMID 24528513, 2014).
pancreatic cancer (continued). "Glucagon-like peptide-1 Receptor (GLP-1R) agonists and dipeptidyl peptidase-4 (DPP-4) inhibitors have also been associated with thyroid and pancreatic cancer." (PMID 24278227, 2013). "One meta-analysis reported no excess risk for pancreatic cancer in patients with T2D using GLP-1R agonists compared with placebo or other antihyperglycemic drugs." (PMID 41178720, 2025). "As with thyroid cancer, GLP-1R agonist use has been linked to pancreatic cancer risk, although without clear consensus on the direction." (PMID 41178720, 2025). "Some studies have shown that differences in the expression of GLP-1R on the surface of different pancreatic cells may affact the development of pancreatic cancer." (PMID 39371922, 2024). "Furthermore, ABCC8/KCNJ11, DPP4, GLP1R, PRKAB1, and GPD2 shared causal variants within anal cancer, HCC, ICC, pancreatic cancer, and rectum cancer according to the colocalization analyses." (PMID 38504335, 2024). "Thereafter, the expression of the GLP-1R on pancreatic tumors was quantified using autoradiography." (PMID 24528513, 2014). "This lack of cell proliferation even after activation of functional GLP-1R may be a result of GLP-1R expression in the transduction pathway activation in pancreatic cancer cells." (PMID 21773024, 2011). "Patients receiving combination therapy that included GLP-1R agonists had a lower risk for pancreatic cancer when compared with those on single, non–GLP-1R therapy, but not when the combination therapy was compared with GLP-1R monotherapy, suggesting a specific antitumor effect of GLP-1R activation." (PMID 41178720, 2025). "The conclusions of later cohort studies or meta-analyses were inconsistent, reporting either no excess risk or an elevated pancreatic cancer risk associated with GLP-1R therapies; however, the risk may be influenced by the severity of T2D." (PMID 41178720, 2025). "Increased ductal cell turnover and ductal metaplasia may predispose to pancreatic cancer risk although one short-term study involving human pancreatic cancer cell lines did not result in cell proliferation with activation of GLP-1R signaling." (PMID 21773024, 2011). "Adult male mice were given a high-fat diet and assigned to receive semaglutide, retatrutide (GLP-1R/GIPR/GCGR triple agonist), dietary calorie restriction, or vehicle control before implantation of pancreatic cancer cells." (PMID 41178720, 2025). "In pancreatic cancer, LINC01121 is shown to inhibit cell apoptosis and promote cell proliferation, migration and invasion via interaction of GLP1R in the control of the Camp/PKA signaling pathway." (PMID 30619763, 2018). "Based on these results, it is not possible to link the difference in GLP-1R expression with the development of pancreatic cancer." (PMID 39371922, 2024). "GLP-1R expression was not related to the prognosis of patients with esophageal squamous cell carcinoma, colon cancer, hepatocellular carcinoma, ovarian cancer, or pancreatic cancer." (PMID 41178720, 2025). "Moreover, in individuals suffering from pancreatic cancer, tumors that exhibit GLP-1R are notably smaller in size compared to those that do not express GLP-1R, indicating a possible reduction in tumor size due to GLP-1R signaling." (PMID 39429275, 2024). "Notably, GLP1R expression appears to have no significant impact on overall survival in cancers such as esophageal squamous cell carcinoma, head-neck squamous cell carcinoma, renal papillary cell carcinoma, liver hepatocellular carcinoma, lung adenocarcinoma, ovarian cancer, and pancreatic cancer." (PMID 39777709, 2025). "Interestingly, there have been suggestions regarding GLP-1R activation inhibiting tumorigenesis and metastasis via the PI3K-Akt signaling pathway, although this was the case for general pancreatic cancer rather than pancreatic NENs." (PMID 40361517, 2025).